MBL3P (mannose-binding lectin family member 3, pseudogene)
Synonyms: COLEC2; MBL
Gene: Unprocessed pseudogene on chromosome 10 (79,582,298 to 79,584,877, reverse strand). Ensembl gene ENSG00000219430.
Diseases named in the same sentence as MBL3P in open-access papers:
MBL3P is named in the same sentence as 1 disease in open-access papers, as found by Europe PMC text mining. Sharing a sentence is not in itself a finding about the gene and the disease.
MBL3P shares sentences with these, for which no sentence is quoted: mastitis (1 paper).